PSPH (phosphoserine phosphatase)
Diseases named in the same sentence as PSPH in open-access papers (continued):
Sharing a sentence is not in itself a finding about the gene and the disease.
Neu-Laxova syndrome (2 papers, 2020 to 2023). Neu-Laxova syndrome (NLS) is a rare, multiple malformation syndrome characterized by severe intrauterine growth retardation (IUGR), severe microcephaly with a sloping forehead, severe ichthyosis (collodion baby type), and facial dysmorphism. "Genetic deficiency in the de novo serine biosynthesis genes PHGDH, PSAT1, and PSPH, in humans causes Neu-Laxova syndrome (NLS), a very rare autosomal recessive congenital disorder." (PMID 32549981, 2020). "Mutations PHGDH, PSPH, and PSAT1 in the serine-glycine pathway have been associated with Neu-Laxova syndrome, which is characterized by a spectrum of phenotypes that vary in expression but usually manifests by perinatal lethality, microcephaly, skeletal, and skin anomalies." (PMID 36737727, 2023).
non-small cell lung carcinoma (2 papers, 2019 to 2021). A group of at least three distinct histological types of lung cancer, including non-small cell squamous cell carcinoma, adenocarcinoma, and large cell carcinoma. "Furthermore, PHGDH, PSAT1, PSPH, and SHMT have been shown to be direct transcriptional targets of ATF4 which was transcriptionally activated by NRF2 in a non-small-cell lung cancer model." (PMID 31615983, 2019).
prostate carcinoma (2 papers, 2021 to 2023). A carcinoma that arises from epithelial cells of the prostate gland. "Although our RNA-Seq analysis identified NEPC as a cancer subtype in which NKX2–1 mutations are associated with increased PSPH mRNA expression, we did not further investigate this cancer subtype, due to the limited availability of prostate cancer models with neuroendocrine origin." (PMID 36932191, 2023).
bone metastasis (1 paper, 2014). Transfer of a neoplasm from its primary site to bones. "The factors associated with shorter OS were Glut-1 positivity (p = 0.020), CAIX positivity (p < 0.001), and PSPH positivity (p = 0.011) in bone metastasis." (PMID 25496516, 2014).
colon cancer (1 paper, 2021). "Since many of these proteins including NPM1, RanBP1, eIF4E and PSPH were previously reported to be transcriptional targets of c-Myc, expression of c-Myc in colon cancer cell lines differing in their BRAF mutational status was also examined." (PMID 34201061, 2021).
Diabetes (1 paper, 2012). "Specifically we examined the Insulin-like Growth Factor Receptor 1, (IGFR1) Mucin 20, (MUC20), Ras Related Associated with Diabetes, (RRAD), and the Phosphoserine Phosphatase (PSPH) genes using qRT-PCR." (PMID 22783543, 2012).
epilepsy (1 paper, 2024). A brain disorder characterized by episodes of abnormally increased neuronal discharge resulting in transient episodes of sensory or motor neurological dysfunction, or psychic dysfunction.
gastric cancer (1 paper, 2022). A primary or metastatic malignant neoplasm involving the stomach. "We observed that PSPH expression displayed considerably high in gastric cancer and it was significantly associated with inferior prognosis (P = 0.043)." (PMID 34979926, 2022). "In summary, PSPH may help to predict prognosis in patients with gastric cancer and is associated with immune cells." (PMID 34979926, 2022). "Moreover, this study revealed that the mechanism of action of PSPH as an indicator of poor outcome in gastric cancer was associated with immune cell infiltrations." (PMID 34979926, 2022). "Furthermore, a univariate Cox analysis identified PSPH expression as a risk factor associated with the prognosis in gastric cancer." (PMID 34979926, 2022). "This study highlighted that PSPH influences the prognosis of patients with gastric cancer, and this is associated with the infiltration of tumour immune cells, indicating that PSPH may be a new immune-related target for treating gastric cancer." (PMID 34979926, 2022). "It was observed in the study that PSPH expression was higher in patients with gastric cancer than in normal individuals." (PMID 34979926, 2022). "In this study, we analysed PSPH expression across multiple cancers using Pan-Cancer data and focused on the relationship between PSPH expression and gastric cancer." (PMID 34979926, 2022). "We conducted Kaplan–Meier survival analysis to elucidate the roles of PSPH expression in gastric cancer." (PMID 34979926, 2022). "We collected and analysed RNA-seq data of Pan-cancer and gastric cancer in the TCGA dataset and PSPH expression data obtained from immunohistochemical analysis of 243 patients with gastric cancer from Sun Yat-sen University cancer center." (PMID 34979926, 2022). "Through data analysis, we found that patients with gastric cancer with high expression of PSPH and low immune score had poor prognosis because of a high amount of M0 macrophages and a low amount of M1 macrophages, which was consistent with the previous study." (PMID 34979926, 2022). "In this study, we examined the prognostic role of metabolic gene PSPH in gastric cancer based on the TCGA dataset and our hospital–based cohort cases." (PMID 34979926, 2022). "Further, we carried out immunohistochemical analysis to detect the PSPH expression in gastric cancer." (PMID 34979926, 2022). "Collectively, this study demonstrated that the metabolic gene PSPH could affect the density of immune cells in patients with gastric cancer, and it could be an important clue for deciding treatment regimens." (PMID 34979926, 2022). "It confirmed that PSPH may participate in the regulation of the tumour immune microenvironment in gastric cancer." (PMID 34979926, 2022). "Similarly, we found high PSPH expression in most of the patients with gastric cancer who had a dismal survival." (PMID 34979926, 2022). "Additionally, we also examined the relationship between PSPH expression and the clinicopathological characteristics of patients with gastric cancer such as invasive depth and distant metastasis (P < 0.001 and P = 0.012, respectively)." (PMID 34979926, 2022). "To assess the expression of PSPH in gastric cancer, we further analysed TCGA-STAD cohort data." (PMID 34979926, 2022). "However, very little is known about the prognostic role of PSPH in patients with gastric cancer." (PMID 34979926, 2022). "Furthermore, we speculated that the underlying mechanism of action was due to the dysregulation of PSPH–immune axis, which might provide a new treatment regimen for patients with gastric cancer." (PMID 34979926, 2022). "This indicated that PSPH could affect the infiltration of immune cells in gastric cancer." (PMID 34979926, 2022).
Juvenile onset (1 paper, 2022). Onset of signs or symptoms of disease between the age of 5 and 15 years. "Of note, a few patients with PHGDH or PSPH mutations prominently showed juvenile-onset peripheral neuropathy and mild neurodevelopment disorders." (PMID 36061210, 2022).
male infertility (1 paper, 2025). The inability of the male to effect fertilization of an ovum after a specified period of unprotected intercourse. "Notably, mutations in the PSPH gene have been associated with severe male infertility, particularly oligoasthenozoospermia (OA), a condition characterized by low sperm count and reduced motility." (PMID 39846682, 2025).
medulloblastoma (1 paper, 2022). A malignant, invasive embryonal neoplasm arising from the cerebellum. "Two of the 5 selected linear fusions in cerebellum, namely SEPTIN7P14--PSPH and PAUPAR--RCN1, were also found in medulloblastoma." (PMID 35804907, 2022).
metastatic prostate carcinoma (1 paper, 2025). A carcinoma that arises from the prostate gland and has spread to other anatomic sites. "Notably, while PSAT1 and PSPH exhibited no change in expression by PLK1, PHGDH showed a significant decrease in our experimental models of advanced metastatic prostate cancers." (PMID 40475404, 2025).
neuroblastoma (1 paper, 2022). Neuroblastoma (NB) is the most common solid, extracranial childhood tumor. "Patients and Methods: The TARGET dataset (n = 151) and our hospital-based cases (n = 55) were used for assessing the expression level of PSPH associated with survival in neuroblastoma patients, respectively." (PMID 36092735, 2022). "Here, we show that the functional role and potential mechanism of PSPH and it is correlated with survival of neuroblastoma patients." (PMID 36092735, 2022). "Specifically, high PSPH expression was found to be negatively associated with CD8+ T cell, macrophages and neutrophils, which negatively affected survival of neuroblastoma patients (p < 0.0001, p = 0.0005, and p = 0.0004, respectively)." (PMID 36092735, 2022). "In summary, these results show that the important of PSPH in neuroblastoma growth and metastasis and prognosis prediction." (PMID 36092735, 2022). "Then, in vitro experiments were performed to define the role of PSPH in neuroblastoma." (PMID 36092735, 2022). "Phosphoserine phosphatase (PSPH), an enzyme of the serine metabolism pathway, has been shown to affect patients’ prognosis in many cancers but its significance in neuroblastoma remains unknown." (PMID 36092735, 2022).
papillary thyroid carcinoma (1 paper, 2021). "In addition, the BRAFV600E mutation status was shown to be associated with the serine biosynthesis pathway in other cancer types including papillary thyroid carcinoma, where higher expression of PSPH and other serine metabolism-related proteins was found in BRAFV600E-mutated tumors." (PMID 34201061, 2021).
psoriasis (1 paper, 2026). An autoimmune condition characterized by red, well-delineated plaques with silvery scales that are usually on the extensor surfaces and scalp. "In vitro experiments demonstrated that knockdown of PSPH could reverse the therapeutic effects of MSCs on psoriasis." (PMID 41904508, 2026).
rectum cancer (1 paper, 2022). "Additionally, overall survival (OS) was plotted using patient-derived data from rectum cancer patients and made the distinction between low and high expression of PHGDH, PSAT1 and PSPH." (PMID 36291844, 2022).
rheumatoid arthritis (1 paper, 2021). A chronic, systemic autoimmune disorder characterized by inflammation in the synovial membranes and articular surfaces. "As a result, expression of ATF4, PSPH, and ASCT1 was upregulated in peripheral blood mononuclear cells of patients infected with rotavirus 21 and in synovial macrophages in patients with rheumatoid arthritis 22 compared to their respective healthy controls." (PMID 34045514, 2021).
serous ovarian cancers (1 paper, 2012). "We next confirmed in a public array set of 39 serous ovarian cancers the expression of PSPHL preferentially in AA cancers compared to CA and no change in PSPH." (PMID 22783543, 2012).
squamous cell carcinoma (1 paper, 2019). A carcinoma arising from squamous epithelial cells. "Consistent with our data, PSPH was significantly overexpressed across the two datasets (P = 0.000 in both adenocarcinoma and squamous cell carcinoma)." (PMID 30977310, 2019).
cancer (54 papers, 2012 to 2025). A tumor composed of atypical neoplastic, often pleomorphic cells that invade other tissues. "The third SSP enzyme, phosphoserine phosphatase, is associated with poor therapeutic response of ER+ breast cancers to tamoxifen, and acts as an oncogene in various types of malignant tumors, including non-small-cell lung carcinoma (NSCLC)." (PMID 37376060, 2023). "The key SSP enzymes PHGDH, PSAT1, and PSPH are significantly overexpressed in a variety of cancers and are associated with poor patient outcomes." (PMID 36699468, 2022). "PSPH exhibits different expression patterns in many cancers and has been associated with the poor prognosis of patients with various cancers, including gastric cancer." (PMID 36175487, 2022). "Growing evidence indicates that high phosphoserine phosphatase (PSPH) expression is associated with tumor prognosis in many types of cancers." (PMID 30977310, 2019). "Autophagy phenomena is highly associated with PSPH expression in cancers, implicating that PSPH expression is important in gastric cell physiology and the interaction with Helicobacter, as evident from genetic polymorphisms in the population that predispose to the disease." (PMID 34979926, 2022). "Collectively, these findings support PSPH as a promising and druggable therapeutic target in cancer treatment." (PMID 41415540, 2025). "Copy number gain or overexpression of PHGDH and PSPH are found in several cancer types, including ER-negative breast cancers, melanoma, lung adenocarcinoma, T-cell ALL and osteosarcoma." (PMID 38698089, 2024). "Some novel therapeutic agents targeting serine metabolic pathways (e.g., PHGDH, PSAT1, and PSPH) in cancer seem to have great potential." (PMID 37187454, 2023). "In the TCGA-generated RNA-seq data on 9,704 cancer samples of 32 human cancer types, we observed a substantially different expression of PSPH among cancer types." (PMID 34979926, 2022). "This differential expression pattern indicated the biological significance of PSPH across multiple cancers." (PMID 34979926, 2022). "Phosphoserine phosphatase (PSPH) exhibits different expression patterns in many cancers and has been reported to affect the prognosis of patients with cancer." (PMID 34979926, 2022). "Studies have also indicated that increased PSPH expression was observed in many cancers including breast cancer, colorectal cancer, gastric cancer, hepatocellular carcinoma, melanoma, and non-small cell lung cancer." (PMID 36092735, 2022). "Recent studies have shown that PSPH is highly expressed in a variety of cancers and mediates malignant behaviors such as tumor proliferation, metastasis, and poor prognosis." (PMID 36699468, 2022). "Although PHGDH, PSAT1 and PSPH have been identified as prognostic biomarkers of a variety of cancers, including GBMs, if they can serve as potential biomarkers of LGGs has not been extensively studied before." (PMID 31861486, 2019). "Phosphoserine phosphatase; inorganic pyrophosphates have a role in energy transduction, DNA replication and other metabolic processes that usually deregulate in cancer cells." (PMID 28246447, 2017). "Notably, PSPH mRNA expression was positively correlated with CNV in multiple cancers, including GBM." (PMID 40660426, 2025). "Potential mechanisms might be related to cMyc-regulated enzymes like glutathione (GSH) and phosphoserine phosphatase (PSPH), which promote redox hemostasis for cancer cells and activate the serine biosynthesis pathway." (PMID 37635935, 2023). "The potential mechanism might be related to cMyc-regulated enzymes like glutathione (GSH) and phosphoserine phosphatase (PSPH), which promote redox hemostasis for cancer cells and activate the serine biosynthesis pathway." (PMID 37635935, 2023).
cancer (continued). "PHGDH and the other enzymes in the serine synthesis pathway—phosphoserine aminotransferase 1 (PSAT1) and phosphoserine phosphatase (PSPH)—can also be activated in cancer cells by epigenetic mechanisms and by the transcription factor ATF4 downstream of both mTOR and Nrf2 signaling." (PMID 31096630, 2019). "Importantly, we show that PSPH is essential for the proliferation of NKX2–1 expressing cancer cells, and we uncover that NKX2–1 overexpressing cells are sensitised to metabolic drugs, including the dual SHMT1/2 inhibitor sertraline and the topoisomerase II inhibitor etoposide." (PMID 36932191, 2023). "Moreover, tumor-related protein p73 (TRP73), hypoxia-inducible factor (HIF)-1, specificity protein 1, and nuclear transcription factor Y have been reported to induce the expression of PHGDH, PSAT1, and PSPH, which contribute to regulating serine biosynthesis and metabolism in cancer cells [,61]." (PMID 37187454, 2023). "This indicates that PSPH may serve as a biomarker for prognosis in cancers." (PMID 34979926, 2022). "This pathway consists of three sequential enzymes: phosphoserine aminotransferase 1 (PSAT1), phosphoserine phosphatase (PSPH), and PHGDH, the rate‐limiting enzyme extensively studied as a cancer therapy target." (PMID 40552664, 2025). "Inhibition of PSPH, the terminal enzyme in the SSP, effectively suppresses key malignant phenotypes in cancer." (PMID 41415540, 2025). "Critically, PHGDH, PSAT1, PSPH, SLC1A4, SLC1A5 and SLC38A2 show robust co‐expression patterns in both TCGA tumour samples and CCLE cancer cell lines, suggesting coregulated functionality." (PMID 40660426, 2025). "In particular, we noted that cancer-related genes including METTL1, ALKBH2, PSPH, PTPRC, and TRIP13 contributed the most to the identification, which indicated the great biological interpretability of our model." (PMID 38243719, 2024). "High expression of serine metabolism-related enzymes, such as phosphoglycerate dehydrogenase (PHGDH) and phosphoserine phosphatase (PSPH), is observed in aggressive cancer subtypes." (PMID 38785550, 2024). "Increased intracellular serine pools in cancer cell lines appeared to result from the over-expression of PHGDH and PSPH, which are involved in intracellular serine biosynthesis." (PMID 37299011, 2023). "By regulating the expression of PHGDH, PSAT, PSPH, and other metabolic enzymes in the serine synthesis pathway (SSP), cancer cells catabolize Ser to sustain their survival." (PMID 34445444, 2021). "Upregulation of the metabolic genes (ALDH18A1, CAD, CHKA, POLD4, PSPH, and SQLE) and aberrant expression of cancer-related genes (ALCAM, ITGA6, DDIT3, MAP3K6, and PAK1) were found in mouse fed with high-fat-high-cholesterol similar to human NASH-HCCs." (PMID 31795276, 2019). "From a literature review, overexpression of PHGDH, PSPH and PSAT1 proteins are known to lead to poor outcomes in various cancers." (PMID 31861486, 2019). "The current study deserves further investigation provided for whole mechanisms by which HT protects cancer cells against oxidative stress through the actions of multiple enzymes such as PHGDH38, PSAT156,57, PSPH and phosphorylated PKM239,58." (PMID 29674746, 2018). "We demonstrated for the first time the aberrant expression of cancer-related genes (ALCAM, ITGA6, DDIT3, MAP3K6 and PAK1) and metabolism-related genes (ALDH18A1, CAD, CHKA, POLD4, PSPH, SQLE and CFD) in human NASH-HCCs." (PMID 30367044, 2018). "The authors demonstrated that deprivation of glucose or glutamine, two major nutrition sources for cancer cells, led to the enhanced c-Myc expression, which in turn activated the expression of three key enzymes of serine synthesis, PHGDH, PSAT1 and PSPH." (PMID 28177894, 2017). "There are also evidences of de-regulated expression in cancer of two other enzymes of serine biosynthesis – PSAT1 and PSPH." (PMID 28177894, 2017).